ERBB2 (erb-b2 receptor tyrosine kinase 2)
Diseases named in the same sentence as ERBB2 in open-access papers (continued):
Sharing a sentence is not in itself a finding about the gene and the disease.
breast cancer (continued). "Also, a synergistic growth inhibitory relationship between trastuzumab and inhibitors of IGF signaling including small molecule inhibitors of IGF-IR, IGFBP-3 and a dominant negative IGF-IR has been established in ErbB2 overexpressing human breast cancer cell lines." (PMID 20825649, 2010). "Well recognized molecular subtypes of breast cancer such as hormone receptor negative and ERBB2 over-expressing tumors are known to be associated with reduced survival, and it will be necessary to extensively examine methylation markers stratified by commonly used molecular tumor markers." (PMID 20686660, 2010). "Therefore, the expression profiles of the genes of the TNFAIP1/POLDIP2 SFGM and the ERBB2 CR are correlated in breast cancer and this fact could probably be explained by co-amplification of their genomic regions." (PMID 20158880, 2010). "Since ErbB-2 over expression may occur also in other epithelial cancers, we performed a comparative staining of HER-2 and htid in non mammary carcinomas characterized by elevated levels of ErbB-2 (10 cases) and in cancers displaying low levels of the receptor (8 cases)." (PMID 20565727, 2010). "Thus, the expression profiles of cell adhesion molecules in pen/lgl2 larvae resemble several human breast carcinomas including an inflammatory breast cancer (IBC), a highly aggressive subtype of human breast cancer, which has been characterized by E-cad and erbB2 over-expression." (PMID 19911055, 2009). "In addition we have used immortalised mammary ductal cells and non-invasive breast cancer cells, where ErbB2 is at low levels, both in their naïve state and when forced to mimic aggressiveness as represented by the in vitro behaviour of the cells which overexpress ErbB2." (PMID 19133120, 2009). "Consequently, most patients with BRCA1-mutated breast cancer do not benefit from therapeutics that target ER- or ERBB2/HER2-expressing tumour cells." (PMID 19904273, 2009). "This and the fact that salubrinal or more powerful derivates like Sal003 do not appear to have significant toxicities in murine models may warrant further investigation into whether Salubrinal or similar molecules that target GADD34-PP1C could be used to treat breast cancers with amplified ErbB2." (PMID 19754954, 2009). "Here, the authors could show that Gab2 expression levels were elevated in mammary tumours induced by the Neu (ErbB-2) oncogene suggesting that an oncoprotein-distorted signalling network alone might be sufficient to up-regulate the expression of Gab2, e.g. via increased E2F activity." (PMID 19737390, 2009). "This present study indicates that there is a sub-population of prostate cancer patients that express erbB-2 and have its pathway activated; such patients could possibly benefit from current anti-erbB2 therapies, such as Herceptin, currently in use in breast cancer." (PMID 18350153, 2008). "A rational approach to the evaluation of these new anti-ErbB2 immunoagents as potential antitumour agents is the comparison of their properties with those of Herceptin (trastuzumab), now established as a powerful therapeutic tool for ErbB2-overexpressing breast cancer, and other carcinomas." (PMID 17923870, 2007). "Benusiglio and colleagues explored ERBB2 haplotypes composed of five tagSNPs [three of which were TAG2, TAG3 and TAG5 in our study] – including the nonsynonymous I655V and P1170A – in relation to the risk of breast cancer, whereas Han and colleagues solely studied the I655V and P1170A as tagSNPs." (PMID 17132159, 2006). "Hence, we did not confirm the finding of Han and colleagues who found that an ERBB2 haplotype composed of two nonsynonymous tagSNPs – I655V and P1170A – increased the risk of breast cancer death or recurrence." (PMID 17132159, 2006). "However, breast cancer overexpression of both ErbB2 and ER is not uncommon and is associated with a different and clinically troublesome phenotype." (PMID 16784538, 2006).
breast cancer (continued). "However, ERBB2 is part of a wider region of chromosome 17q21 frequently amplified in breast cancer." (PMID 17117180, 2006). "In our population, common ERBB2 polymorphisms are not involved in predisposition to breast cancer." (PMID 15743501, 2005). "The scFv(ErbB-2)/ζ fusion gene was stably expressed in murine T lymphocytes that subsequently could recognise and lyse either mouse cell lines transfected to express the human ErbB-2 receptor or the human breast cancer MDA-MB453 cell line constitutively expressing ErbB-2." (PMID 12698199, 2003). "Since the upregulation of NUPR1 correlates with poor clinical outcomes in ER+ and ERBB2 (HER2)-enriched breast cancer patients, we sought to further confirm the role of NUPR1 in the induction of estrogen independence in ER+ breast cancer cells." (PMID 39991577, 2025). "MIEN1 (P < 1 × 10–6 in both secondary screens) is a regulator of cell migration and invasion located near ERBB2 and frequently amplified in HER2-positive breast cancer." (PMID 40165206, 2025). "For example, in breast cancer, bi-CAR-T cells targeting ErbB2 and MUC1 in vitro, showed efficient antitumor activity." (PMID 40861448, 2025). "The epidermal growth factor receptor 2 (HER2, also known as ERBB2), a member of the HER family of receptor tyrosine kinases, is overexpressed in 15–20% of primary breast cancers including 10% of estrogen receptor (ER)-positive breast cancers." (PMID 39934835, 2025). "Concerning HER2, its gene ERBB2 has been found to be genetically amplified in approximately 15% to 20% of breast cancer patients." (PMID 39941808, 2025). "For example, the tyrosine kinase ErbB2 (HER2), a key driver in certain breast cancer subtypes, enhances the expression and activity of both NHE1 and NBCn1 via the ERK-RSK signaling pathway." (PMID 41515572, 2025). "Amplification and overexpression of ERBB2 (also known as HER2), have been extensively documented in various human solid tumors, including breast cancer, ovarian cancer, gastric cancer, and salivary gland tumors." (PMID 40919374, 2025). "The group also showed that treating SKBR3 and HCC1954 breast cancer cells with lapatinib (inhibitor of EGFR/ErbB1 and ErbB2) led to a decrease in PHLDA1 as assessed by immunoblotting." (PMID 39630301, 2025). "Specifically, module I is highly activated in the six DCIS areas identified in the original study, representing the spatial expression of breast cancer markers such as SPINT2, FXYD3, and ERBB2." (PMID 40033360, 2025). "Erbin, which interacts with Erbb2, is downregulated in HER2-overexpressing breast cancer cells and it can form a complex with NOD2 to inhibit RIPK2 activity." (PMID 40406369, 2025). "Additionally, targeting ERBB2 (such as the use of Trastuzumab) could be an effective treatment for patients originally diagnosed with luminal A breast cancer with subsequently found to exhibit luminal B-ERBB2+ characteristics and resistance to endocrine therapy after prolonged treatment." (PMID 39991577, 2025). "Another team developed a TNBC xenograft model in zebrafish larvae and generated two CAR-NK cell lines targeting PD-L1 and ErbB2 to combat MDA-MB-231 breast cancer cells expressing PD-L1 and MDA-MB-453 breast cancer cells expressing ErbB2." (PMID 40705122, 2025).
breast cancer (continued). "Acquired resistance to endocrine therapy is a major clinical challenge in the treatment of luminal A [estrogen receptor (ER)+ and/or progesterone receptor (PR)+, human epidermal growth factor receptor 2 (ERBB2/HER2)-, and low Ki-67] breast cancer." (PMID 39991577, 2025). "The presence or absence of three receptors is particularly important when determining the type of breast cancer: the estrogen receptor (ESR1), the progesterone receptor (PGR), and the HER2 epidermal growth factor receptor (ERBB2)." (PMID 40143151, 2025). "Monocyte_1_IL1B exhibited a strong correlation with mechanistically related pathways, such as the ERBB2 − EGFR signaling pathway, which has been reported to promote the proliferation and migration of breast cancer cells." (PMID 41233852, 2025). "The upregulated differentially expressed breast cancer stem cell markers included CD56/NCAM1, POU5F1, PROCR/CD201, ITGA6, and the downregulated were ESR1, PGR, HER2/ERBB2, ABCG2, CD44, CD24, EPCAM, and CDH1." (PMID 40690373, 2025). "We also examined the spatial correlation between the expression of ERBB2, SLC9A3R, and EZR in breast cancer cells, using a spatial transcriptomics (visium) database of human breast cancer." (PMID 40390040, 2025). "We applied this sample clustering approach across 100 breast cancer IMC samples and found remarkable concordance with clinical metrics such as ER status and ERBB2-positive patients, even though we used only 37 protein markers." (PMID 40841370, 2025). "A recent study revealed frequent copy number gain or amplification of HOXB13, including co-amplification with ERBB2, as a mechanism driving increased HOXB13 expression in a subset of breast cancer." (PMID 40137996, 2025). "TGFB1, ERBB2, and CD68 form a signaling network that impacts cancer progression, invasion, and resistance to therapy in HER2-overexpressing breast cancer tumors." (PMID 41373732, 2025). "Three breast cancer cell lines, BT-474 (ErbB2-overexpression and trastuzumab-sensitive), SK-BR-3 (ErbB2-overexpression and trastuzumab-resistant), and MCF7 (ErbB2-low-expression), were selected for trastuzumab treatment." (PMID 39786928, 2025). "The application prospects of ERBB2 (HER2) inhibitors, common in breast cancer treatment strategies, are also receiving much attention in bladder cancer." (PMID 39911393, 2025). "Downregulation of NUPR1 by siRNA decreased the amount of both the ERBB2 mRNA transcripts and the ERBB2 proteins present in the ER+ ERBB2high MCF7-TamC3 and the ER- ERBB2high (ERBB2-enriched subtype-like) SK-BR-3 breast cancer cells." (PMID 39991577, 2025). "Amplification or overexpression of ERBB2/HER2 leads to uncontrolled cell growth and is a major driver of certain aggressive breast cancers." (PMID 40806432, 2025). "The Ku70/Ku80 complex was previously also shown to interact with TFAP2A in breast cancer cell lines, in which recruitment of Ku70 together with TFAP2A was needed for the transcriptional activation of the ERBB2 proximal promoter." (PMID 39994865, 2025). "Erb-b2 receptor tyrosine kinase 2 (ERBB2), progesterone receptor (PGR), and estrogen receptor (ER) are three key receptors frequently used to classify breast cancers." (PMID 40141415, 2025). "Human epidermal growth factor receptor 2 (HER2) is a protein that is overexpressed because of HER2 (ERBB2) gene amplification and plays a crucial role in the development and progression of breast cancer." (PMID 41269400, 2025). "Trastuzumab is a monoclonal antibody that targets the ERBB2 (erb-b2 receptor tyrosine kinase 2)/HER2 receptor, which is overexpressed in certain breast cancers." (PMID 39817564, 2025). "In the PPI network of 308 genes, several hub genes (ESR1, BRCA1, CREBBP, ERBB2, and LCK) are known to play critical roles in breast cancer development." (PMID 39888956, 2025).
breast cancer (continued). "In a recent study, leveraging metadata from over 5870 breast cancer lesions, the authors showed that individuals with high germline epitope burden in ERBB2 were less likely to develop HER2 positive breast cancer compared to other subtypes." (PMID 40236693, 2025). "A major subtype, triple-negative breast cancer (TNBC), is characterized by the lack of expression of estrogen receptor (ER), progesterone receptor (PR), and HER2 (ERBB2), and accounts for approximately 15 % of all breast cancer cases." (PMID 40822245, 2025). "On the other hand, the migratory subtype showed shared characteristics with Luminal A and Normal-like classification, as they had low expression of known breast cancer markers such as ESR1, PGR and ERBB2." (PMID 38892065, 2024). "Recent advancements, notably the emergence of HER2-targeted ADC, have demonstrated improved survival outcomes in breast cancer patients with HER2 IHC scores of 1+ or 2+ (HER2-low when combined with knowledge of negative ERBB2 amplification status)." (PMID 38395930, 2024). "PTP1B is also known to modulate the effects of ErbB2 and PTK, which is especially important as overexpression of ErbB2 and PTK manifests in as much as 72–90% of all breast cancers." (PMID 39000142, 2024). "Interestingly, our study showed that the median ERBB2 copy number in MaBC is significantly lower than in FBC, highlighting additional molecular differences in HER2-positive breast cancer between males and females which may impact sensitivity to anti-HER2 therapy." (PMID 39049124, 2024). "In this context, our study sought to investigate the prognostication capability of a 22‐gene mutational profile obtained through targeted sequencing in women with ER+/ERBB2‐ EBC, whose primary breast cancer specimens were retrievable from a tissue bank." (PMID 39031010, 2024). "For example, the United States Food and Drug Administration (FDA)-approved drugs (Level 1) are available for alterations in ERBB2, PIK3CA for breast cancer and other biomarkers such as MSI-High, TMB-High for all solid tumors." (PMID 39706915, 2024). "This kinome reprogramming involved RTKs including FGFR2, ERBB2 and MET that were heterogeneously upregulated in different HER2+ breast cancer cell lines growing in the presence of lapatinib." (PMID 39513002, 2024). "In breast cancer, the transmembrane MUC1‐C‐terminal subunit (MUC1‐C) interacts with EGFR, ErbB2, and other receptor tyrosine kinases and contributes to the activation of the PI3K→AKT and MEK→ERK pathways." (PMID 38778448, 2024). "Certain targets were enriched in specific cancer types as expected based on the clinical treatment landscape or tumor biology (eg, EGFR, MET, ROS1, MET, and ALK in NSCLC; or ERBB2, CDK4, CDK6, aromatase, and ER in breast cancer)." (PMID 37682776, 2024). "Over 20% of ER-positive/ERBB2(HER2)-normal and ERBB2-amplified exhibited cyclin D1 gene amplification in breast cancer patient data from The Cancer Genome Atlas (TCGA)." (PMID 39095874, 2024). "ERBB2 targeted therapies are widely used to treat breast cancer and are being investigated for use in CRC, and there are multiple trials investigating the efficacy of ERBB2-targeted therapies in metastatic CRC." (PMID 39001533, 2024). "Interaction between Hsp90 and the extracellular domain of HER2/ErbB2 through the activation of the Akt, SRC and ERK pathways can lead to breast cancer cell invasion." (PMID 38672583, 2024). "In breast cancer, it has been reported that radiation or endocrine therapy upregulates ERBB2 gene transcription in HER2-low or HER2-negative subtypes, leading to treatment resistance." (PMID 39641248, 2024). "In breast cancer brain metastases, recurrent gene expression losses in ESR1 (ER) and gene expression gains in ERBB2 (HER2) have been attributed to Luminal (ER+) intrinsic subtype switching." (PMID 39090418, 2024).
breast cancer (continued). "Human epithelial growth factor receptor‐2 (HER2, also known as ERBB2) is an important biomarker that affects breast cancer prognosis and treatment decisions." (PMID 38272454, 2024). "Heterotrimerization of erbB3/erbB2/IGF-IR blocked trastuzumab binding and activated PI3K/AKT signaling pathway and Src kinase, which resulted in trastuzumab resistance in breast cancer cells." (PMID 38835349, 2024). "When applied to transcriptome data from breast cancer patients, the eCOT identified EGFR/ERBB2 and multiple EGFR-related downstream targets as enriched in estrogen-receptor positive (ER+) breast cancers likely to recur late (≥ 5 years after initial diagnosis)." (PMID 38853832, 2024). "The second major molecular target in breast cancer is epidermal growth factor 2 (ERBB2, previously known as HER2 or HER2/neu), a transmembrane receptor tyrosine kinase belonging to the epidermal growth factor receptor family." (PMID 39065193, 2024). "Among the cell lines are all relevant breast cancer subtypes, which are luminal/hormone receptor positive (HR+), HER2/ERBB2 positive (ERBB2+) and basal/triple negative breast cancer (TNBC)." (PMID 38187472, 2024). "Herein, we demonstrated that miR‐449‐5p decreases the expression level of ERBB2, hence inhibiting cell proliferation and invasion through the JAK/STAT pathway in breast cancer." (PMID 38351535, 2024). "Around 15% of all breast cancer cases overexpress the human epidermal growth factor receptor 2 (ERBB2 or HER2) and is therefore referred to as HER2+ (HER2 positive) breast cancer." (PMID 38784015, 2024). "DeePathNet was able to highlight known biomarkers when predicting breast cancer subtypes, including ESR1, ERBB2, and the FOXM1 network pathways." (PMID 39530738, 2024). "In breast cancer cells, Ku70 collaborates with AP2, being recruited to the proximal promoter of ERBB2 for transcription regulation." (PMID 39446493, 2024). "Our results underscore the complexity of the ERBB2 signaling pathway and suggest new therapeutic opportunities by identifying potentially effective drugs and combinations in HER2-positive breast cancer." (PMID 39684551, 2024). "It comprises 20–30% of all breast cancers and is characterized by overexpression of the human epidermal growth factor receptor 2 (HER2, HER2/neu, ERBB2) oncogene." (PMID 38542136, 2024). "This study aimed to systematically re-assess HER2 biomarkers including HER2 ISH and ERBB2 mRNA, and correlate them to outcomes in trastuzumab-treated early HER2-positive breast cancer patients." (PMID 38321542, 2024). "Copy number alterations have long been an identified feature of several cancers; prominent examples include ERBB2 (HER2) amplification, observed in nearly 20% of breast cancer cases, and MYCN amplification, estimated in 25% of neuroblastoma cases." (PMID 39095874, 2024). "In this cell line, the PROTACs suppressed the residual expression of ERBB2/HER2, 3 and 4 that are essential for the proliferation of breast cancer cells and this cell line proved sensitive to HER2 inhibitors." (PMID 38896334, 2024). "The HER2 gene, also known as Neu, ErbB2, or CD340, was initially identified in human breast cancer cells." (PMID 39655080, 2024). "In the clinic, breast cancer is screened for the presence of estrogen receptor (ER), progesterone receptor (PR) and amplification of ERBB2/HER2 (HER2)." (PMID 37776423, 2024). "SRC‐1 upregulates the expression of ERBB2, colony‐stimulating factor 1 and TWIST1 thereby promoting metastasis in breast cancer." (PMID 38506084, 2024). "Of all subtypes, HER2-positive overexpresses the human epidermal growth factor receptor type 2 (EGFR2, ErbB2, or HER2) and comprises 15–25% of total breast cancer cases." (PMID 38431613, 2024). "HER2 overexpression, which arises from the amplification of the ERBB2/neu proto‐oncogene located on the centromere of chromosome 17 (CEN17), is found in approximately 15%–20% of breast cancers." (PMID 38234171, 2024).